TTC32 (tetratricopeptide repeat domain 32)
Tractability: PROTAC: ubiquitination databases record sites on it.
Gene: Protein-coding gene on chromosome 2 (19,896,631 to 19,902,001, reverse strand). Ensembl gene ENSG00000183891.
Subcellular location (Human Protein Atlas): Mitochondria; Nucleoplasm
Gene Ontology:
Molecular function: protein binding
Genetic constraint (gnomAD): Loss-of-function variants: 15 observed, 13.78 expected, observed/expected ratio (o/e) 1.09, 90% interval 0.73 to 1.65. The upper end of that interval is the gene's LOEUF score, 1.65, which puts it in group 6 of 6, group 1 being the genes least tolerant of losing a copy. Missense variants: 167 observed, 166.37 expected, observed/expected ratio (o/e) 1, 90% interval 0.88 to 1.14. Synonymous variants: 82 observed, 65 expected, observed/expected ratio (o/e) 1.26, 90% interval 1.05 to 1.52.
Homologues: Orthologues: chimpanzee TTC32 (99% identical), macaque TTC32 (95% identical), guinea pig TTC32 (85% identical), pig TTC32 (83% identical), dog TTC32 (81% identical), mouse Ttc32 (75% identical), rat Ttc32 (72% identical), rabbit TTC32 (65% identical), tropical clawed frog ttc32 (56% identical), zebrafish ttc32 (51% identical), Drosophila melanogaster unc-45 (19% identical), Caenorhabditis elegans unc-45 (18% identical), and 1 more. Paralogues in human: SPAG1 (23% identical), TTC4 (23% identical), STIP1 (22% identical), TTC1 (22% identical), DNAAF4 (20% identical), RPAP3 (20% identical), SGTB (20% identical), STUB1 (19% identical), TOMM34 (19% identical), TTC31 (19% identical), UNC45B (19% identical), SGTA (18% identical), and 6 more.
Diseases named in the same sentence as TTC32 in open-access papers:
TTC32 is named in the same sentence as 1 disease in open-access papers, as found by Europe PMC text mining. Sharing a sentence is not in itself a finding about the gene and the disease.
TTC32 shares sentences with these, for which no sentence is quoted: coronary artery disease (2 papers).